CCR2 (C-C motif chemokine receptor 2)
Diseases named in the same sentence as CCR2 in open-access papers (continued):
Sharing a sentence is not in itself a finding about the gene and the disease.
colitis (continued). "Moreover, COX2, PGE2, and CCR2 would be plausible future targets to investigate in the CNS of animals with colitis, given their role in the progression of events relevant to neuroinflammation." (PMID 34983592, 2022). "The reduced severity of colitis observed in IL10R-deficient mice lacking CCR2 was accompanied by a significant reduction in the number and frequency of immature Ly6C+ colonic macrophages compared to mice lacking IL10R alone." (PMID 35013585, 2022). "Furthermore, some in vivo works demonstrate a beneficial effect in experimental colitis when the number of CCR2+ cells is reduced in the inflamed colon and peripheral blood." (PMID 36009431, 2022). "In this study, we investigated whether irbesartan, which potentially acts as a direct CCR2 antagonist, prevents colitis, intestinal fibrosis and tumourigenesis, in an azoxymethane (AOM) and dextran sodium sulphate (DSS) mouse model of colitis-associated CRC29." (PMID 34620946, 2021). "Moreover, blockade of MCP-1/CCR2 pathway in haematopoietic cells by using CCR2RFP/RFP-BM chimeric mice ameliorates colitis and prevents the intestinal fibrosis." (PMID 34620946, 2021). "Finally, mice in whom monocyte recruitment to the inflamed mucosa is defective due to deletion or neutralization of CCL2, CCR2 or β7 integrin are protected from DSS-induced colitis." (PMID 30538701, 2018). "Interestingly, the protein expression of PSMP was up-regulated on the third day in this colitis model, which paralleled the elevation of the CD11b+CCR2+ monocytes." (PMID 28698550, 2017). "Therefore, our results revealed that PSMP is a chemokine that triggers the earlier-arriving Ly6ChiCCR2+ monocyte migration from the circulation into the tissue that depends on CCR2 and further promotes colitis." (PMID 28698550, 2017). "However, the key chemokine that initiates the CCR2+ monocytes migration from circulation to colitis tissue remains to be undiscovered." (PMID 28698550, 2017). "Despite data showing that migration of LTi ILC3s from the gut to the mesenteric lymph nodes is dependent on CCR7 expression, expression of CCR7 on ILCs was not assessed in that study and we were unable to identify CCR7 or CCR2 on intestinal ILC3s in anti-CD40 induced colitis." (PMID 26780670, 2016). "In contrast, significance of CCL2/CCR2 in colitis models has been established." (PMID 24714157, 2014). "Studies should entice to investigate whether CCR2 is upregulated in brain tissue from animals with colitis, which may help elucidate possible mechanisms underpinning microglial activity seen in animals with colitis." (PMID 34983592, 2022). "CCR2-deficient animals were not protected from severe colitis by Norovirus infection." (PMID 34188111, 2021). "Furthermore, we show that the severity of the pathology of Salmonella- induced colitis as well as the nitrate-dependent growth of Salmonella in the lumen of the inflamed intestine are reduced in mice that lack Ccr2 and, therefore, inflammatory monocytes in the tissues." (PMID 31306468, 2019). "Although a previous study has reported attenuated DSS-induced colitis by simultaneous blockage of chemokine receptors CCR2, CCR5 and CXCR3, we demonstrate that CXCR3-deficient (KO) mice alone challenged with dextran sulfate sodium (DSS) are resistant to the development of experimental colitis." (PMID 24992040, 2014). "In this study, we observed that both CCR2+GMSCs and GMSCs notably decreased IFN-γ or IL-17 secreting CD4+T lymphocytes when compared with untreated colitis rats." (PMID 40472038, 2025). "Surprisingly, Tgfb1, Il17ra, Il23a, Il6ra, Ror1, Tnf, Tgfbr2, Ccr2, and Il17c were downregulated by cigarette smoke exposure in TNBS-induced colitis Gpr15−/− mice compared with similarly treated Gpr15+/+ mice." (PMID 40957881, 2025). "CCR2 (i.e., CCL2 receptor) on Ly6Chi monocytes recruits them to the inflamed intestinal lamina propria in experimental colitis models, where they become the predominant mononuclear cell cluster." (PMID 39200138, 2024).
colitis (continued). "Lysozyme-expressing CD102+ (ICAM2)+ macrophages are recruited in a CCR2- and antibiotic-independent manner to the colon in DSS-induced colitis and have been proposed to promote intestinal repair." (PMID 37876927, 2023). "As shown by ANOVA, the gene expression of Ccr1, Ccr2, Ccr5, and Cxcr2 was higher in the rats with TNBS-induced colitis than in the control group (p < 0.001)." (PMID 35163326, 2022). "Thus, our data demonstrate that the reduced severity of colitis observed in mice lacking both IL-10RA and CCR2 is associated with a decrease in the accumulation of colonic macrophages and a decrease in the proportion of immature macrophages observed within this population." (PMID 35013585, 2022). "Of these, CCL2 is known to be an important ligand for CCR2, though its role in colitis is unclear, as DSS treated Ccl2−/− mice have been shown to develop either exacerbated or ameliorated colitis." (PMID 30542349, 2018). "To date, targeting of chemokine receptors such as CCR2, CCR5, CCR6, CXCR3, CXCR4 and CX3CR1 by gene disruption or antagonistic peptides has been found to protect animals from DSS colitis." (PMID 21283540, 2011). "Importantly, adoptive transfer of WT CCR2+ monocytes to DKI mice delayed the onset and ameliorated the severity of colitis following DSS administration, and the disease course in DKI mice the received WT monocytes was comparable to the WT mice." (PMID 37153611, 2023). "Moreover, L. acidophilus NCFM and FAHWH11L56 showed similar effects on various indicators of DSS-induced colitis, increasing the IL-10 and IL-17 in the colon, and modifying the CCL2/CCR2 axis and CCL3/CCR1 axis." (PMID 36499169, 2022). "In a recent paper using the murine colitis model, it was shown that the absence of CCR2 has differential effects in different contexts (e.g., using IL10R−deficient mice), demonstrating the complexity of the system." (PMID 36341422, 2022). "The gene expression of Ccr2, Ccr5, and Cxcr2 was increased in colitis rats fed with feed without beta-glucan (βG−) compared to the control group (HβG−) at both time points, whereas Ccr1 gene expression was increased only after 3 days of TNBS administration." (PMID 35163326, 2022). "Our data demonstrate that the absence of CCR2 reduces the severity of colitis in mice lacking IL-10R signaling." (PMID 35013585, 2022). "We also subjected Cx3cr1GFP/+Ccr2RFP/+ mice to DSS-induced colitis and found that no CCR2+ and/or CX3CR1+ signal co-localized with the large F4/80hi cells indicating that these are distinct cell lineages." (PMID 34911964, 2021). "Infiltration of Ly6Chi monocytes seems to be crucial for the development of the intestinal pathology: defects in the recruitment of monocytes into the inflamed mucosa, due to the deletion or neutralization of CCL2, CCR2, or β7 integrin pathways, result in a less severe DSS-induced colitis." (PMID 32650452, 2020). "Unfortunately, it is not possible to test the CCR2 dependency of the hBD2 effect in vivo because CCR2−/− mice are protected from experimental induced colitis." (PMID 32076420, 2020). "The homing functions were owing to the fact that MSCs expressed many chemotaxis receptors such as CCR1, CCR2, CCR4, CCR5, CCR9, CXCR1, and CXCR5; the CCR2 and CCR4 were major migration helpers of MSCs in colitis, and CXCR4 combined with SDF-1 can promote MSCs migration." (PMID 30687760, 2018). "Nevertheless, it is important to note that CCR2 may not govern monocyte migration in all contexts, as accumulation of Ly6Chi monocytes and their progeny is unaffected by CCR2 deficiency in H. hepaticus induced colitis and CCR1 plays a key role in monocyte migration during acute toxoplasmosis." (PMID 30538701, 2018). "In the case of colitis, the potential for R243 to block both CCL2 (MCP-1)/CCR2-driven chemotaxis and CCL1 might enhance the anti-inflammatory effect in comparison with that of CCR8-/- mice." (PMID 24714157, 2014).
colitis (continued). "Here, we asked whether CCR2 is necessary for the development of colitis in mice lacking the receptor for IL10." (PMID 35013585, 2022). "However, no changes in seizure threshold in colitis mice with impaired CCR2 functioning were found, which suggested that monocytes do not play a major role in colitis-induced neuronal hyperexcitability." (PMID 34983592, 2022). "However, we found that the histological signs of colitis were less severe in Cdcs1+/+ mice that lacked both Il10ra and Ccr2 than in littermates that lacked Il10ra alone." (PMID 35013585, 2022). "Therefore, blocking the signal transmission in CCL2/CCR2 axis and CCL3/CCR1 axis might be an important method for L. acidophilus FAHWH11L56 to potentially relieve colitis." (PMID 36499169, 2022). "For L. acidophilus FGSYC48L79, although it blocked the CCL2/CCR2 axis, it can promote the signal transmission on the CCL3/CCR1 axis, which may be one of the reasons why this strain appeared to have the effect of worsening colitis." (PMID 36499169, 2022). "The absence of CCR2 interfered with the accumulation of immature macrophages in IL10R-deficient mice, including a novel population of rounded submucosal Iba1+ cells, and reduced the severity of colitis in these mice." (PMID 35013585, 2022). "Therefore, we suggest that the absence of CCR2 interferes with the development of colitis in mice lacking the receptor for IL10 without altering the expression of its ligand CCL2." (PMID 35013585, 2022). "We speculated that the redundancy of PSMP, CCL2 and CCL7 in colitis might result in that CCR2 but not the CCL2 is vital to the progression of colitis." (PMID 28698550, 2017). "Thus, it remains unclear whether CCR2 function and CCR2-dependent monocyte recruitment are necessary for the development of colitis in mice lacking IL-10R signaling." (PMID 35013585, 2022). "One team found that similar colitis can be induced in CCL2 KO mice and wild types, which indicated that the effects of CCR2 in colitis are independent of CCL221." (PMID 28698550, 2017). "Lack of CCR2 in mice abrogates the recruitment of TLR2+ CCR2+ Gr-1+, TNF-α-producing macrophages to the inflamed intestine, and reduces symptoms of DSS-induced colitis." (PMID 36675038, 2023).
melanoma (58 papers, 2011 to 2025). A malignant, usually aggressive tumor composed of atypical, neoplastic melanocytes. "RT-qPCR assays demonstrated that Ccl2/Ccr2 and Cxcl9/Cxcl10/Cxcr3 levels were higher in B16 melanoma tumors from Cbx3/HP1γ-deficient mice than those from controls." (PMID 34721405, 2021). "We have previously reported that VPA can significantly reduce CCR2-expressing M-MDSCs, specifically by reducing their accumulation in tumors and inhibiting the growth of lymphoma and melanoma." (PMID 39891718, 2025). "These Ccr2+ monocytes were also found to be key contributors in directing melanoma cell reprogramming towards specific therapeutic resistance pathways." (PMID 40058234, 2025). "C-C chemokine receptor type 2 (CCR2) macrophages infiltrate tumors, creating an immunosuppressive environment that supports melanoma survival by releasing pro-tumor cytokines." (PMID 40872475, 2025). "MPO directly showed activation of PMN by binding to the CD11b receptor, while HOCl triggered inhibition of NF-κB and subsequent CCR2 expression in keratinocytes and melanoma cells." (PMID 38736886, 2024). "We found CCR2-RFP expression around melanoma cells only in mice that received BM cells from Ccr2RFP/+ (top row) mice, but not Ccr2RFP/RFP mice, confirming that knockin mutation of Ccr2RFP/RFP prevents egress of I-NCMs into the established metastatic colonies." (PMID 39545417, 2024). "On the other hand, a CCR2-deficient TME delayed the onset of resistance and shifted melanoma cells to a more sensitive state to targeted therapy." (PMID 38533720, 2024). "The therapeutic block of the CCL2/CCR2 axis has yielded promising results to slow the progression of several tumor types; the therapy of melanoma-targeting CCR2 inhibited tumor growth in laboratory animals." (PMID 35269787, 2022). "We demonstrated that melanoma cells gained the ability to overexpress CCR2 in response to MCP-1 oversecretion, enhancing their tumorigenic properties in vitro." (PMID 35980743, 2022). "In summary, we propose that inhibition of CCR2 reduces the recruitment of early-stage MR-Ly6C+ pro-inflammatory macrophages, which leads to enhanced survival and progression of metastasising melanoma cells." (PMID 36241867, 2022). "The role of CCR2 (activated by its ligands) in the induction of migration and invasion in tumor cells including melanomas has been reported in recent studies." (PMID 35269787, 2022). "Here, CCR2 expressed by melanoma derived from the brain was 7-fold higher compared with melanoma in the skin, whereas a 2-fold increase was observed for CCR4’s expression." (PMID 35980743, 2022). "In humans, both primary and metastatic melanomas, but not normal skin, express MCP-152, and antagonism of its receptor CCR2 enhanced the therapeutic efficacy of anti-PD-1 antibody in a murine melanoma model." (PMID 35665759, 2022). "Melanomas inducing expansion of CCR2-expressing monocytic-MDSCs in the TME by producing CCL2, activating MDSCs through MAPK signaling." (PMID 34095111, 2021). "This, in turn, recruited CCR2+ immune cells, most notably macrophages and myeloid-derived suppressor cells (MDSCs), which are able to support melanoma growth through multiple mechanisms." (PMID 34830780, 2021). "In previous studies, we established that TAMs are the most abundant type of myeloid cells in melanoma tissues, as compared with other mononuclear (CCR2+ monocytes or CD1c+ myeloid DCs) and polymorphonuclear phagocytes." (PMID 34439098, 2021). "BRAF inhibitor-resistant melanomas induced expansion of CCR2-expressing monocytic-MDSCs in the TME by producing CCL2, activating MDSCs through MAPK signaling." (PMID 34095111, 2021). "According to our study, coexpression of CCR2, CFLAR, PRKCQ, and LINC00324 was associated with autophagy in melanoma." (PMID 34250091, 2021). "CCR2-targeted drugs have also been tested, for example, CCR2-targeted apoptotic peptide was used in the therapy of melanoma in laboratory animals." (PMID 33182504, 2020).
melanoma (continued). "CCR2 appears to be an attractive target in melanoma and potentially in other tumor types and a CCR2 antibody, plozalizumab, is currently being tested in phase I clinical trial (NCT02723006) in combination with an immune checkpoint blocker, nivolumab." (PMID 30420855, 2018). "Upon UVB exposure, melanoma cells start producing chemokine receptor type 2 (CCR2) ligands that recruit CCR2-expressing macrophages to the skin." (PMID 28798748, 2017). "In vivo BRAF-mutant melanoma models with fluorescent markers to track stage-specific changes in macrophages under targeted therapy with BRAFi/MEKi, showed a rise in CCR2+ macrophage infiltration at the onset of a drug-tolerant persister (DTP) state after several weeks of treatment." (PMID 38533720, 2024). "CCR2+ M-MDSCs suppress CD8 T cells in a murine melanoma model." (PMID 39338937, 2024). "Importantly, this phenotype was reversed with the introduction of CCR2+ macrophages in the TME of melanoma." (PMID 38533720, 2024). "However, melanocytes in neonatal skin and UVB-initiated melanoma cells are protected from immune-mediated killing by IFN-γ that is secreted by CCR2+ macrophages." (PMID 38304252, 2023). "Overwhelming evidence supported targeting the CCL2–CCR2 axis in various cancer types including in melanoma as candidates for immunotherapy, especially in combination with ICBs, which also echoes our results of correlations between the expression of CCR2 and IC genes." (PMID 37404751, 2023). "Moreover, in vitro, we found that MCP-1 secreted from astrocytes or recombinant murine MCP-1 (rm-MCP-1) directly induced the expression of CCR2 in B16-F10 melanoma cells, otherwise poorly expressed in the absence of MCP-1 stimulus." (PMID 35980743, 2022). "Here, we used this advanced melanoma model to assess whether the CD11b+CCR2+ cell played a role in the BG34-200-AF647 accumulation in tumor." (PMID 36497393, 2022). "Use of combination therapies, potentially including CDDO-Me, that target the CCL2/CCR2 axis may inhibit the development of treatment resistance in melanoma." (PMID 35265066, 2022). "Subsequent studies have shown increased infiltration and anti-tumor responses of adoptively transferred mouse and human T cells engineered to express, for instance, CCR4, CXCR2 and CCR2 in transplantable mouse models of Hodgkin’s lymphoma, melanoma and mesothelioma, respectively." (PMID 28923105, 2017). "In contrast, deficiency of Ccr2 abrogated γδT17 cell infiltration of B16 melanomas but did not affect their expansion in draining lymph nodes (LNs)." (PMID 28580944, 2017). "Additionally, CCR2-mediated infiltration of both Vγ4+ and Vγ6+ γδT17 cells into B16 melanomas suggests that this axis is a universal inflammatory homing signal for γδT17 cells." (PMID 28580944, 2017). "We propose that the MCP-1/CCR2 axis be considered an immune checkpoint regulator involved in melanoma-astrocyte and brain cell interactions that may drive and facilitate the establishment of an immunosuppressive microenvironment in which melanoma cells can take control, grow, and disseminate." (PMID 35980743, 2022). "Melanoma cells were found to alter the astrocyte secretion and evoke CCL2 expression and secretion, which in turn induced CCR2 expression in melanoma cells and enhanced their in vitro tumorigenic properties such as proliferation and metastasis." (PMID 37307835, 2024). "We postulate that the classical CD16− monocytes are recruited into the melanoma TME, likely via tumour-derived CCL2, where they upregulate CD163 and gradually lose the expression of CD14 and CCR2." (PMID 38903497, 2024). "Periostin is a potent (CCR2+) BMDM recruiter, as evident from studies on glioblastoma and primary melanoma lesions." (PMID 37240029, 2023). "Recently, a KLAK-MCP-1 micelle composed of CCR2-targeted peptide sequence and apoptosis-inducing KLAK peptide inhibited melanoma growth in B16F10 mouse models by inhibiting MCP-1/CCR2 axis and decreasing the recruitment of TAMs." (PMID 37600822, 2023).